NDRG2 (NDRG family member 2)
Diseases named in the same sentence as NDRG2 in open-access papers (continued):
Sharing a sentence is not in itself a finding about the gene and the disease.
NDRG2 also shares sentences with these, for which no sentence is quoted: fibrosarcoma (4 papers); pancreatic cancer (4); adenocarcinoma (2); colitis (2); oral cancer (2); osteosarcoma (2); T-cell leukemia (2); acute lymphoblastic leukaemia (1); anaplastic meningioma (1); cholangiocarcinoma (1); CNS tumor (1); colonic adenomas (1); colorectal tumor (1); deafness (1); diabetic retinopathy (1); dysplasia (1); epilepsy (1); esophageal squamous cell carcinoma (1); gastric tumor (1); gynecological tumors (1); hematological malignancies (1); Hepatic (1); Hypertension (1); Intellectual disability (1); ischemic disease (1); liver cirrhosis (1); mitochondrial disease (1); myocardial infarction (1); skin carcinoma (1); testis cancer (1).